NELL2 (neural EGFL like 2)
Diseases named in the same sentence as NELL2 in open-access papers (continued):
Sharing a sentence is not in itself a finding about the gene and the disease.
tumor (17 papers, 2012 to 2026). "Despite its diverse roles, the context-dependent duality of NELL2-acting as both an oncogene and tumor suppressor, a neuroprotectant and contributor to hyperexcitability-remains mechanistically unclear." (PMID 41993193, 2026). "Nevertheless, genes such as Nell2, Smarca1, Slc6a14 and Grhl3 which were highly downregulated by the combined treatment were reported to contribute to tumor progression." (PMID 39450263, 2024). "Age, N stage, and pTNM stage were identified as risk factors, whereas tumor grade, and B3GNT3, MACC1, NELL2, and USH1G were identified as protective variables." (PMID 38818465, 2024). "B3GNT3, MACC1, and NELL2 showed significantly higher expression in normal tissues than in tumor tissues." (PMID 38818465, 2024). "The third cluster included 18 tumours that showed expression of both NELL2 and LAMA2 (NELL2+/LAMA2+)." (PMID 34314101, 2021). "CST1 and NELL2 proteins were significantly overexpressed in tumour tissues compared with adjacent non-tumour tissues." (PMID 33869274, 2021). "There are very few reports on the relationship between NELL2 and the tumour microenvironment, so it is necessary to study the mechanism by which NELL2 regulates the tumour microenvironment." (PMID 33869274, 2021). "Similarly, multiple studies have shown that TFF3 and NELL2 are significantly upregulated in tumor tissue compared to adjacent normal tissue, promoting tumor migration, growth, and leading to poor prognosis." (PMID 38277205, 2024). "mRNA levels for NELL2 were suppressed in tumour tissues, relative to NATs and GC tissues." (PMID 35957621, 2022). "Furthermore, both NELL1 and NELL2 were increased in tumor tissues with lower ANO5 expression, while the expression of KI67 (a biomarker for proliferation) was decreased." (PMID 34238763, 2021). "Inhibition of ANO5 increased NELL1 and NELL2 expression in vivo and decreased tumor proliferation." (PMID 34238763, 2021). "Additionally, there was inconsistency in the expression of MACC1 and NELL2, which may be due to the high heterogeneity of tumor tissues from different sources." (PMID 38818465, 2024). "The smaller cluster (14.2% of tumours) showed high expression of five genes belonging to the PFB signature and NELL2+/LAMA2− expression pattern." (PMID 34314101, 2021). "Likewise, the following marker genes were selected for analysis in PF tumours: LAMA2, ALDH1L1, SLC6A13, IGSF1, and CXorf67 for PFA; and NELL2, DNAH1, CEP83, C9orf72, and NXNL2 for PFB tumours." (PMID 34314101, 2021). "The second cluster included 23 tumours showing expression of LAMA2 but not NELL2 (NELL2−/LAMA2+)." (PMID 34314101, 2021). "The first showed seven tumours with expression of NELL2 but not LAMA2 (NELL2+/LAMA2−), which overlapped exactly with tumours from the PFB cluster." (PMID 34314101, 2021).
cancer (10 papers, 2019 to 2026). A tumor composed of atypical neoplastic, often pleomorphic cells that invade other tissues. "The overexpression of two of the OCs, EPYC and NELL2, were associated with minor changes in the cancer transcriptome (≤ 5 differentially expressed transcripts)." (PMID 30820027, 2019). "Here, we consolidated research advances of NELL2, delineating its structural features, regulatory networks, and context-dependent roles in neurodegeneration, immunity, reproduction and cancer." (PMID 41993193, 2026). "We also identified a novel mechanism in addition to DNA hypermethylation by which the tumor suppressors NELL1 and NELL2 were downregulated in cancer tissues." (PMID 34238763, 2021). "We found that mRNA level of NELL2 was downregulated in cancer tissues compared with NATs among 84 cases (three cases did not participate in this analysis due to insufficient cDNAs) of GC tissues." (PMID 33665159, 2020). "Previous studies have shown that NELL2 is enriched in normal nerve cells compared with nervous system tumors and that it inhibits cancer cell migration in renal cell carcinoma." (PMID 33665159, 2020). "NELL2, a neuron-specific secreted glycoprotein, has emerged as a key regulator in multiple physiological and pathological contexts, including neurodegeneration, immunity, reproduction and cancer." (PMID 41993193, 2026). "In contrast, Nakamura and colleagues recently reported a reduction of ROBO3 levels in invasive malignancies of the breast when compared with normal tissues and postulated a negative regulation of metastatic behaviors by Neural EGFL Like 2 (NELL2)/ROBO3-signaling." (PMID 36057630, 2022). "Furthermore, hypermethylation of NELL1 and NELL2, which decreased their transcription, was common in cancer." (PMID 34238763, 2021). "In addition, NELL2 also is enriched in para‐cancer cells and inhibits the growth of clear cells." (PMID 35957621, 2022). "CBX2 and neural EGFL-like 2 (NELL2) have been shown to promote invasion, metastasis, or cell division in a variety of in vivo and in vitro models of cancer." (PMID 30820027, 2019).
nervous system tumors (2 papers, 2021 to 2022). "Relative to nervous system tumours, NELL2 is abundant in normal nerve cells." (PMID 35957621, 2022).
infection (1 paper, 2023). The state of being infected such as from the introduction of a foreign agent such as serum, vaccine, antigenic substance or organism. "The receiver operating characteristic (ROC) curve showed that protein kinase C-binding protein NELL2, thrombospondin-1, and complement factor I have diagnostic potential for differentiating staphylococci and streptococci intramammary infection and inflammation." (PMID 37889706, 2023). "This may point to a potential role of NELL2 protein in the regulation of PKC activity/availability dependent upon calcium concentration in the milk, consequently resulting in the regulation of host immune pathogen-dependent response to the infection of mammary glands." (PMID 37889706, 2023).
neurological disease (1 paper, 2013). "So, by combining specific GO term–annotated gene lists and cross-checking with publications, we were able to decrease the number of candidate genes and predict candidate genes (FOXO4, GRM5, RIMS1 and NELL2) for neurological diseases." (PMID 23794737, 2013).
NELL2 also shares sentences with these, for which no sentence is quoted: colorectal cancer (1 paper); developmental delay (1); dyslexia (1); epilepsy (1); esophageal cancer (1); ganglioglioma (1); immune diseases (1); metastatic cancer (1); metastatic tumor (1); myopathy (1); neurodegenerative disease (1); neurodevelopmental disorder (1); Obesity (1); osteoporosis (1); Sensorimotor neuropathy (1); small cell bladder cancer (1); tuberculous meningitis (1).